CCDC190 (coiled-coil domain containing 190)
Synonyms: C1orf110; MGC48998
Tractability: PROTAC: ubiquitination databases record sites on it.
Gene: Protein-coding gene on chromosome 1 (162,824,458 to 162,868,957, reverse strand). Ensembl gene ENSG00000185860.
Subcellular location (Human Protein Atlas): Actin filaments; Cytosol
Genetic constraint (gnomAD): Loss-of-function variants: 10 observed, 13.85 expected, observed/expected ratio (o/e) 0.72, 90% interval 0.44 to 1.22. The upper end of that interval is the gene's LOEUF score, 1.22, which puts it in group 5 of 6, group 1 being the genes least tolerant of losing a copy. Missense variants: 375 observed, 371.77 expected, observed/expected ratio (o/e) 1.01, 90% interval 0.93 to 1.1. Synonymous variants: 136 observed, 135.36 expected, observed/expected ratio (o/e) 1, 90% interval 0.87 to 1.16.
Homologues: Orthologues: chimpanzee CCDC190 (98% identical), macaque CCDC190 (81% identical), pig CCDC190 (68% identical), dog CCDC190 (65% identical), rabbit CCDC190 (61% identical), guinea pig CCDC190 (58% identical), rat Ccdc190 (54% identical), mouse Ccdc190 (54% identical).
Diseases named in the same sentence as CCDC190 in open-access papers:
CCDC190 is named in the same sentence as 1 disease in open-access papers, as found by Europe PMC text mining. Sharing a sentence is not in itself a finding about the gene and the disease. The quoted sentences say what the papers report.
tumour (1 paper, 2021). "Most ES expressed neurexin-1 (96%) and ELFN2 (96%), whereas SLC38A11 and CCDC190 were detected in just 41% and 67% of the tumours examined, respectively." (PMID 34403115, 2021). "CCDC190 and SLC38A11 were only detected in single or small clusters of ES cells within the tumour, consistent with the hypothesis that these proteins are expressed by ES-CSCs and are, therefore, candidate therapeutic targets to eradicate ES-CSCs." (PMID 34403115, 2021).